ALB (albumin)
Diseases named in the same sentence as ALB in open-access papers (continued):
Sharing a sentence is not in itself a finding about the gene and the disease.
Hypertension (continued). "Multivariate Poisson regression analysis for anemia was performed after adjustment for gender, age, smoking, hypertension, DM, use of ESA, ferritin, transferrin, albumin, total cholesterol, and eGFR." (PMID 29077007, 2017). "In patients with T2DM, serum XOD activity was directly correlated to BMI, the presence of hypertension, and levels of HbA1c, AGE, IMA, and UA and inversely correlated to serum albumin and total thiol groups concentrations." (PMID 27965983, 2016). "Hypertension, age, central obesity defined by WHR, male gender, social class, 2h after blood glucose, albumin creatinine ratio (ACR) and family history were positively associated with CVDs." (PMID 27494706, 2016). "Increased risks were also observed in the pre-frail group for some of these factors, including low HDL-C, hypertension, high WCC, low FEV1, poor renal function and low albumin." (PMID 25480883, 2015). "Subjects with AF had a higher prevalence of electrocardiographic left ventricular hypertrophy, ischemic heart disease, hypertension, renal dysfunction, elevated levels of C-reactive protein (CRP) and increased urinary albumin excretion as compared to controls." (PMID 16623947, 2006). "Subjects with AF had a higher prevalence of electrocardiographic LVH, ischemic heart disease, hypertension, renal dysfunction, and higher levels of CRP and urinary albumin excretion as compared to age and gender matched controls." (PMID 16623947, 2006). "AT-II-induced hypertension from about 100 to 150 mmHg significantly increased the accumulation of the macromolecular drug SMANCS and 51Cr-labelled bovine serum albumin ([51Cr]BSA), representatives of macromolecular drugs, in tumour tissue." (PMID 8494731, 1993). "For pure NDKD, lower HbA1c, lower serum albumin, lower body mass index, higher IgA levels, and absence of hypertension were significant predictors." (PMID 42279208, 2026). "In comparison to obese patients, children with MASLD exhibited significantly higher rates of arterial hypertension and elevated levels of aspartate aminotransferase (AST), alanine aminotransferase (ALT), gamma-glutamyltransferase (GGT), albumin, fasting glucose, and uric acid." (PMID 40084870, 2025). "Finally, we used FIB, ALB, AIP, LDL-C, BMI, classification of DR, gender, and history of hypertension as predictors to construct the nomogram model." (PMID 40391008, 2025). "Similarly, the RBF SVM model utilized ALT, uric acid, body weight, BMI, height, PLT, fasting insulin, total bilirubin, ALB, HbA1c, age, AST, creatinine, TG, LDL-C, DM, sex, TC, HDL-C, and hypertension." (PMID 40361915, 2025). "Retain the 10 variables jointly identified by the two algorithms (such as BMI, neutrophils, platelets, albumin, SII, PNI, AISI, hypertension, multiple pregnancies, and smoking); Add four immune-related indicators unique to the Boruta algorithm (LMR, lymphocytes, NLR, ALI)." (PMID 40606469, 2025). "There was a significant difference between the two groups in terms of APACHE 2 score, RDW-SD, RDW-CV, BUN, creatinine, potassium, magnesium, phosphate, albumin, Crp, APTT, INR, hypertension, oliguria, RRT used, vasopressor requirement, sepsis, and mechanical ventilation treatment." (PMID 40731862, 2025). "Multivariable Cox regression, adjusted for age, sex, BMI, dialysis vintage, DM, hypertension, serum albumin, and the non-HDL combination group, revealed that age was an independent risk factor for stroke (HR: 1.040, 95% CI: 1.021–1.059) in our cohort." (PMID 41517492, 2025). "Compared to the normoglycemia group, the iIFG and IGT groups were significantly associated with higher weight, BMI, WC, systolic and diastolic BP, HbA1c, fasting glucose, HOMA‐IR, albumin, ALT, GGT, and TC levels, as well as a higher frequency of hypertension and dyslipidemia." (PMID 40855982, 2025). "Nine non-zero coefficient variables were identified: age, hypertension, DM, smoking, neutrophil count, lnPIV, ALB, LDL-C, AIP, and RC." (PMID 40951434, 2025).
Hypertension (continued). "Significant differences were identified in age, sex, race/ethnicity, BMI, poverty income ratio, physical activity, depression, DM, hypertension, CVD, CKD, statins, diuretics, total cholesterol, triglycerides, platelets, neutrophils, and albumin across the four study groups." (PMID 40898257, 2025). "Various characteristics included age, sex, weight, smoking status, drinking status, fibrinogen, TBIL, TP, AST, ALT, ALB, GGT, ChE, ALP, TBA, GLU, CREA, urea, TC, HDL, Lp(a), PLT, WBC, neutrophil count, APTT, TT, PT-INR, PT, hypertension, HLP, liver disease, and DM (P < 0.05)." (PMID 40334204, 2025). "In this retrospective, cohort study, the PAR, a combined index of PDW and serum albumin, was assessed to determine its independent effects on clinical adverse outcomes in patients with hypertension, which have not been investigated sufficiently." (PMID 40593009, 2025). "After adjusting for age, gender, hypertension, non-alcoholic fatty liver disease (NAFLD), hemoglobin, albumin, smoking history, alcohol consumption history, and body mass index (BMI), lnIns60/ApoA was an independent influence factor for ACR ≥ 30 mg/g(OR = 2.778, p = 0.015)." (PMID 41140685, 2025). "In contrast, patients who achieved complete or partial remission after rituximab treatment had higher baseline serum albumin levels (3.6 – SD 1.0 vs 2.8 – SD 0.9), no diagnosis of hypertension (12.5%), and were steroid-sensitive (100%)." (PMID 41020481, 2025). "Univariate analysis revealed that 289 patients with MASLD with ALT levels ≤ 30 U/L in both cohorts were older than those with stages 0–2, with significant differences in age, type-2 DM, hypertension, AST levels, platelet counts, albumin levels, HbA1c levels, and the FIB-4 index." (PMID 40647590, 2025). "The association between the red cell distribution width-to-albumin ratio (RAR), a newly identified inflammatory biomarker, and hypertension has not been systematically evaluated in population-based studies." (PMID 40783688, 2025). "Compared with normal LV diastolic function group, the LV diastolic dysfunction group had higher age and BMI, as well as lower heart rate, lower serum albumin, lower eGFR, higher serum TgAb and BNP level, and the incidences of hypertension were also higher (all P <0.05)." (PMID 38375196, 2024). "The univariate analysis revealed that the following factors were significantly associated with prolonged LOS: age, sex, insurance type, ACCI score, hypertension, OP, PI, analgesics use, antibiotics use, psychotropic drug use, AKP, DBIL, TC, TGs, NLR, LMR, PLR, CREA, LDL-C, HDL-C, and ALB (p < 0.05)." (PMID 39148703, 2024). "Three studies reported no impact on hypertension-related outcomes such as preeclampsia, gestational hypertension, or urine albumin-to-creatinine ratio." (PMID 38564247, 2024). "Additionally, proteins such as AGT, ALB, APOL1 and UMOD had the highest disease scores (76–100% confidence) for hypertension and CKD." (PMID 38402394, 2024). "Moreover, we confirmed that patients who underwent mechanical ventilation had a longer illness time, higher hypertension, less CRP and albumin, higher amounts of urea, and worsened pulmonary function (according to the PaO2/FiO2 and A-a O2 gradients)." (PMID 38838044, 2024). "Model 3c was adjusted for covariates from Model 2b as well as hypertension (“Yes” or “No”), hemoglobin, serum albumin, and uric acid." (PMID 38567310, 2024). "In this model, biomarkers such as sex, hypertension, homocysteine levels, neutrophil-to-HDL ratio (NHR), history of stroke, and albumin-to-globulin (A/G) ratio were incorporated, all of which have been shown to correlate significantly with the occurrence of CMBs." (PMID 39734492, 2024). "There was a linear negative correlation between albumin and sarcopenia in the under 45 years, male, with or without hypertension and without DM population." (PMID 39096855, 2024).
Hypertension (continued). "Patients with MACE exhibited significant differences in ALC, ALB, preoperative PNI, age, BMI, CRP, TG, presence of comorbidities (hypertension, hyperlipidemia, pulmonary infections), history of prior PCI, smoking status, LVEF, Cr, and intervention programs, in comparison to those without MACE." (PMID 39068452, 2024). "Model 3: adjusted for sex, age, BMI, hypertension, cerebrovascular disease, peripheral vascular diseases, anemia, DM, previous myocardial infarction, previous PCI, previous CABG, LDL‐C, creatine, albumin, HbA1c, left ventricular ejection fraction, left main or three‐vessel disease, and SYNTAX score." (PMID 39136595, 2024). "Recently, several studies have investigated the risk factors for postoperative renal dysfunction in patients undergoing adrenalectomy for PA, including preoperative eGFR, urinary albumin excretion, ARR, age, serum potassium level, BMI, and hypertension duration." (PMID 39574955, 2024). "Compared with subjects with normal LV diastolic function, subjects in the LV diastolic dysfunction group had higher age and BMI, as well as lower heart rate, lower serum albumin, lower eGFR, higher serum TgAb and BNP level, and the incidences of hypertension were also higher (P<0.05)." (PMID 38375196, 2024). "When compared to the quartile I-WWI group, the quartile II-WWI, quartile III-WWI, and quartile IV-WWI groups showed significant increases in age, annual household income under $20,000, prevalence of hypertension, cardiovascular disease, BMI, Weight, WC, BUN, SUA, urinary albumin, and UACR (P<0.01)." (PMID 38559695, 2024). "Between the two groups,there were statistically significant differences in age, hypertension, previous strokes, WBC, neutrophil, monocyte, eosinophil, albumin, BUN, Cr, free IL-2, IgA, IgG, CRP, C4 (p < 0.05), and the other factors were not significantly different (p > 0.05)." (PMID 38887608, 2024). "Notably, of all SVD markers studied, only the presence of ≥ 10 CMBs was significantly related to death after adjustment for age, sex, hypertension, cardiac disease, GCS, albumin, and any complication." (PMID 36810469, 2023). "Variables that were considered potential predictors of overall early complications on univariate analysis included age, BMI, sex, ASA score, T2D, hypertension, dyslipidemia, OSAS, GERD as well as the following laboratory parameters: plasma creatinine, albumin, ferritin and hemoglobin." (PMID 36484858, 2023). "Our study further performed smooth curve-fitting based on stratified analysis, and found that the negative correlation between serum albumin and CHD risk was more pronounced in women, the participants over 60 years of age, and those with hypertension." (PMID 36635398, 2023). "In addition, a medical history of hypertension, minimum SBP, minimum hemoglobin, albumin and tacrolimus maximum trough level were significantly associated with AKI during admission." (PMID 36968791, 2023). "A larger decline in eGFR is more common in patients with hypertension, a lower (but within normal range) albumin level, and a higher baseline eGFR, but not DAA treatment." (PMID 36766578, 2023). "However, the proportion of patients with serum ALB<LLN, especially the proportion of patients with cirrhosis as well as T2DM, were significantly higher than those in the non-hypertension group (all P<0.05)." (PMID 38027142, 2023). "In primary cohort, the univariate analysis showed that age, hypertension, stroke, histological grade, TNM stage, preoperative albumin, preoperative LMR, postoperative LMR, dynamic LMR change and intraoperative RBC transfusion were significant prognostic factors." (PMID 37519800, 2023). "At baseline, six IgAVN patients had hypertension and seven patients had mildly reduced serum albumin levels (range of abnormal values 22–39 g/L) without evidence of peripheral oedema or clinical significance." (PMID 38046006, 2023).
Hypertension (continued). "Differences in the proportion of males, age, incidence of hyperlipidemia, incidence of hypertension, current smoking, alcohol consumption, waist circumference, hip circumference, TC, TG, LDL-C, HDL-C, serum uric acid, serum creatinine, urine albumin and uACR were statistically significant (p <0.05)." (PMID 36829751, 2023). "Heart failure, hypertension, underweight, age at onset, and ileus showed positive direct effects, while albumin and hemoglobin demonstrated negative direct effects." (PMID 38831863, 2023). "Patients treated with corticosteroids and/or immunosuppressive medications had significantly lower serum albumin, higher UPCR, more hematuria, and more hypertension at baseline than patients in the conservative management (observation alone or RAAS blockade alone) groups." (PMID 37316676, 2023). "In addition, we found age, gender, race, hypertension, AST, SCr, and serum albumin persisted as statistically significant factors in relation to the ACR in the fully adjusted model." (PMID 37710270, 2023). "In our work, we constructed a predictive nomogram on the basis of six independent prognostic parameters (hypertension, histological grade, TNM stage, preoperative albumin, preoperative LMR and dynamic change in LMR) identified by the backward stepwise cox regression analyses." (PMID 37519800, 2023). "Compare with patients without DR, patient with DR had a lower proportion of males, longer DM duration, lower BMI, lower serum levels of ALB, ALT, AST, higher levels of BUN and D-dimer, and higher probability of hypertension, dyslipidemia, renal insufficiency and DME." (PMID 37336896, 2023). "Furthermore, weak effect sizes were found in term of patients’ age, coronal artery disease, and albumin, whereas moderate correlations were identified in the COPD variables, BMI, tumor classification, and arterial hypertension." (PMID 37658335, 2023). "In this study, we established a predictive model and incorporated the following 12 variables into its construction: age, preoperative serum albumin, ASTI, preoperative CRP level, hypertension, IBL, IMBP, CCD, history of smoking, history of alcohol consumption, PD, and the AIMBPD." (PMID 36258311, 2023). "Compared with patients with strict-normal thyroid function, those with low thyroid function were more likely to be older, females; with a higher prevalence of T2DM and hypertension; with higher levels of total cholesterol, HDL, fasting glucose, and lower levels of ALT, GGT, and albumin." (PMID 36604612, 2023). "In the univariate analysis, factors that were identified to be significant predictors of the risk of HCC in NASH cirrhosis were older age (> 69 years), male sex, overweight/obesity, T2DM, hypertension, FIB-4 >3.25, albumin, INR, total bilirubin, and platelet count." (PMID 37675229, 2023). "Patients in the high LAR group had an older age (p < 0.01), a higher portion of females (p < 0.01), lower BMI (p < 0.01), smoking (p < 0.01), drinking (p < 0.01), hypertension (p = 0.018), higher levels of LDH (p < 0.01), lower levels of albumin (p < 0.01) and lower levels of hemoglobin (p < 0.01)." (PMID 37770882, 2023). "Furthermore, PBC patients with T2DM tended to be older, had lower levels of serum ALB and PLT, and had higher rates of ACA and/or anti-CENP-B, cirrhosis, hypertension, and mortality." (PMID 38027142, 2023). "In the subgroup analysis stratified by gender, race/ethnicity, smoking, high blood pressure, the negative correlation of albumin with CRP was remained." (PMID 37653773, 2023). "On the other hand, complications due to albumin infusion (especially hypertension) are not uncommon, and this leads to recommending albumin infusion only in those patients with diuretic resistance and albumin levels <2 g/dl." (PMID 37675009, 2022).
Hypertension (continued). "2%) tended to be older, had higher rates of hypertension, antiplatelet or anticoagulation, dysphagia, and IVH, and had larger hematoma volumes, lower GCS scores, RBCs, ALC, hemoglobin, and albumin, and higher NIHSS scores, WBCs, ANC, SIRI, NLR, MLR, and PLR in the training cohort (P < 0.05)." (PMID 36712440, 2022). "In univariable analysis, old age, male sex, DM, hypertension, elevated values of SBP, DBP, BMI, fasting glucose, total cholesterol, triglycerides, hemoglobin and uric acid, decreased eGFR, high values of GGT, albumin ALT and AST, and low total bilirubin were correlated with new-onset hyperuricemia." (PMID 36364933, 2022). "In brief, patients with RIS were older, with a higher proportion of hypertension and history of ischemic stroke, higher serum creatinine (Scr) levels, and lower serum albumin and total lymphocyte levels than patients without RIS (all p < 0.05)." (PMID 35405949, 2022). "There were statistically significant differences between the two groups in age, hypertension, Barthel index, VTE, prealbumin, total protein, albumin, globulin, BUN/Scr, LDH, cholinesterase, serum sodium, serum chlorine, WBC, Neutrophils, PT, TT, fibrinogen, and d-dimer (all P values < 0.05)." (PMID 36443675, 2022). "In addition, a high value of fibrinogen was also a powerful independent risk factor for ACS (OR: 1.042 [1.002–1.083)], p<0.05) after adjusting for age, hypertension, family history of CVD and albumin." (PMID 35881574, 2022). "On the contrary, higher platelet (PLT) and higher albumin (ALB) levels were more common in participants without hypertension." (PMID 36225955, 2022). "The most relevant factors in the model of kidney stone development were the albumin creatinine ratio, BMI, serum creatinine, age, non-Hispanic white, high blood pressure, HCV infection status, and so on." (PMID 35991057, 2022). "Patients with sarcopenia were older (p < 0.001) and had higher prevalence of hypertension (p = 0.023) and a lower level of preoperative haemoglobin (p < 0.001) and albumin (p = 0.023) compared with patients without sarcopenia." (PMID 34199110, 2021). "The Cox proportional hazards regression analysis showed that only CMBs ≥ 10 was significantly related to mortality (adjusted HR 2.669, 95% CI 1.248–5.707; p = 0.011) after adjusting for age, sex, hypertension, cardiac disease, GCS, albumin, and any complication." (PMID 33679377, 2021). "There were positive correlations between serum Zn and 24 h urine Zn, history of hypertension, and eGFR (P < 0.05), and negative correlations between a history of smoking, SCr, and ACR and 24 h urine albumin loss (P < 0.05)." (PMID 33859989, 2021). "The preoperative factors associated with evisceration in the univariate analysis were old age, high body mass index (BMI), hypertension, smoking, comorbidities, high American Society of Anesthesiologist (ASA) score (3 and 4), and low preoperative albumin level." (PMID 32927929, 2021). "In this retrospective observational study, a negative correlation between CLC and initial GI involvement was found, independent of age, gender, CRP, albumin globulin ratio, hypertension, and dyspnea." (PMID 33526973, 2021). "In the univariate analysis, PS ≥ 2, hypertension, heart disease, upper GC, CEA ≥ 5, CA19-9 ≥ 37, albumin< 3.5, CRP ≥ 0.5, pT4, pN+, positive lymphatic invasion, positive venous invasion, Neut ≥ 3690, Lymp < 1860, Plt ≥ 27.2 × 104, and SII ≥ 395 correlated with poor OS." (PMID 34118953, 2021). "In model 3, which was a maximally adjusted model including center, age, sex, hypertension, temperature, use of corticosteroid, gamma globulin, AST, ALT, albumin, BUN, eGFR, PCO2, PO2, adjusted HRs for developing to SP were 5.841 (95% CI, 1.566‐21.791, P = .009)." (PMID 33128497, 2021).